VCAM1 (vascular cell adhesion molecule 1)
Diseases named in the same sentence as VCAM1 in open-access papers (continued):
Sharing a sentence is not in itself a finding about the gene and the disease.
atrial fibrillation (13 papers, 2017 to 2026). A disorder characterized by an electrocardiographic finding of a supraventricular arrhythmia characterized by the replacement of consistent P waves by rapid oscillations or fibrillatory waves that vary in size, shape and timing and are accompanied by an irregular ventricular response. "Recently, an association of elevated soluble VCAM-1 levels with new onset of atrial fibrillation (AF) could be shown in a prospective, population-based cohort study with two decades of follow-up." (PMID 30535754, 2019). "Release of soluble VCAM-1 (sVCAM-1) into the circulation has not only been associated with a number of cardiovascular disease processes including human post-operative atrial fibrillation, but is also observed to rise as early as 3 h after routine cardiopulmonary bypass." (PMID 28821262, 2017). "The plasma protein soluble vascular cell adhesion molecule 1 (sVCAM-1) has been suggested as a biomarker for atrial fibrillation (AF)." (PMID 41137671, 2025).
thrombosis (13 papers, 2016 to 2025). "The expression of TGF-β increases after AVF creation and higher expression of VCAM-1 is associated with thrombosis and stenotic AVF." (PMID 36147190, 2022). "Plasma VCAM-1 levels are associated with risk of atherosclerotic disease, but they may also have a potential role in mediating acute venous thrombosis." (PMID 40367073, 2025). "Furthermore, the levels of VCAM-1 were different significantly among control group vs. arterial thrombosis, venous thrombosis, and major bleeding groups (p < 0.05)." (PMID 36211709, 2022). "The baseline levels of IL-6, IL-10, VCAM-1, CCL19, BCA-1, IL-4, E-selectin, fractalkine, CXCL12, and GCP2 were found to differ statistically among the control, arterial thrombosis, AF-related venous thrombosis, and major bleeding groups (p < 0.05)." (PMID 36211709, 2022). "Furthermore, the expression of circulating markers as von Willebrand factor, VCAM-1 and soluble p-selectin have been found to be higher in patients with atherosclerotic lesions and venous thrombosis, suggesting inflammation as the cause and not the consequence of thrombosis." (PMID 39851572, 2025). "Moreover, it has been found that patients with DVT had a much higher concentration of circulating VCAM1 compared to patients without thrombosis." (PMID 34206566, 2021).
Alzheimer disease (12 papers, 2020 to 2026). A progressive, neurodegenerative disease characterized by loss of function and death of nerve cells in several areas of the brain leading to loss of cognitive function such as memory and language. "However, one BBB model did measure adhesion molecule, VCAM-1, in hiPSC-derived pericyte-like mural cells (iMCs) differentiated from an Alzheimer's disease “APOE4/4 risk” line and an “APOE4/4-risk edited to APOE3/3-non-risk” hiPSC line." (PMID 36483299, 2022). "The cell adhesion molecules ICAM-1 and VCAM-1 have been shown to mediate leukocyte migration in aging and age-released degenerative disorders such as Alzheimer’s disease and vascular dementia." (PMID 40427506, 2025). "In a nutshell, these findings revealed ALCAM and VCAM-1 as reliable indicators of Alzheimer’s disease." (PMID 36685605, 2022). "The analysis identifies VCAM1-mediated neuroinflammatory pathways in the superior parietal lobule and CX3CR1-regulated synaptic pruning in the putamen as key pathophysiological hubs in Alzheimer's disease." (PMID 41459562, 2025). "VCAM-1 and IL4Rα surface receptors specific aptamers have been reported and successfully demonstrated for the depletion of myeloid-derived suppressor cells (MDSC) and detection of inflammation in the transgenic mouse model of Alzheimer’s disease, respectively." (PMID 32751068, 2020). "To more quantitatively investigate whether inflammatory reactive astrocytes are specifically adjacent to inflamed vessels, we probed tissue sections from an Alzheimer’s disease (AD) cohort and asymptomatic age-matched controls for GFAP, GBP2, and VCAM-1 expression." (PMID 36323693, 2022).
Cerebral ischemia (12 papers, 2014 to 2025). Restriction of arterial blood supply to the brain associated with insufficient oxygenation to support the metabolic requirements of the tissue. "Expression of the VCAM-1 adhesion molecule has been comprehensively studied as an indicator of inflammation in models of cerebral ischemia." (PMID 35203655, 2022). "Because VCAM-1 mediates sustained and prolonged leukocyte adhesion and transmigration, there is an increasing appreciation for the role of VCAM-1 in coordinating the inflammatory response and leukocyte recruitment in cerebral ischemia." (PMID 33692398, 2021). "In this study, we first demonstrated that the downregulation of CD151 decreased the VCAM-1 on endothelial cells, thereby restraining neutrophil and monocyte infiltration and improving neurological outcomes after cerebral ischemia." (PMID 34022890, 2021). "Herein we report that Poldip2+/− mice exhibit reduced infiltration of leukocytes into the brain, as well as lower VCAM-1 expression, following cerebral ischemia." (PMID 33692398, 2021). "VCAM-1, in turn, which predominantly mediates adhesion of monocytes, progressively increases and peaks 5–10 days after cerebral ischemia, corresponding to the onset of monocyte recruitment." (PMID 33692398, 2021). "Expression of adhesion molecules (e.g., ICAM-1 and VCAM-1) is mediated by activation of the NF-κB pathway, which is typically studied as an indicator of inflammation in models of cerebral ischemia." (PMID 32019570, 2020). "Therefore, the MAPK and NF-κB pathways were involved in the consistent expression of CD151 and VCAM-1 in endothelial cells after cerebral ischemia." (PMID 34022890, 2021). "In addition, HES counteracted the upregulation of proinflammatory cytokines, such as the expression of TNF-α and IL-1β, in cerebral ischemia, as well as IL-8, IL-6, IL-12, and vascular cell adhesion molecule 1 (VCAM-1), in the case of acute lung inflammation induced by LPS in vivo." (PMID 24891765, 2014). "Activated endothelial cells also release E-selectin, vascular cell adhesion molecule 1 (VCAM-1), and intercellular adhesion molecule 1 (ICAM-1), which further support leukocyte binding and migration after cerebral ischemia." (PMID 41245147, 2025). "Here, we examined the expression levels of VCAM-1, ICAM-1, E-selectin, and CD9 in vivo and in vitro to confirm the effects of CD151 on endothelial cell adhesion molecules within the TEMs in cerebral ischemia." (PMID 34022890, 2021). "In cerebral ischemia using the middle cerebral artery occlusion (MCAO) model, a greater area of VCAM-1 expression was detected compared to the DWI hyperintense area, suggesting that hypoperfused brain regions at risk for infarction upregulate VCAM-1." (PMID 25525560, 2014). "In contrast to its effects on the expression of ICAM-1 and VCAM-1 molecules that promote firm adhesion—iNO had no apparent effect on E-selectin or P-selectin expression following cerebral ischemia." (PMID 38102677, 2023). "It seemed that the enhanced KLF4 could suppress the vascular endothelial expression of three CAMs including E-selectin, VCAM-1, and ICAM-1 after cerebral ischemia." (PMID 32264912, 2020).
fibrosis (12 papers, 2019 to 2024). the formation of excess fibrous connective tissue in an organ or tissue in a reparative or reactive process. "This pattern was further validated with quantitative IF analysis, revealing significantly elevated tubular injury markers Krt8 and Vcam1 in Ecad-positive distal nephron tubular segments compared to proximal tubules in both fibrosis models." (PMID 38172172, 2024). "Previous studies have reported an upregulation of VCAM-1 in the liver and specifically in HSCs under inflammatory conditions, e.g., upon LPS administration or CCl4-induced fibrosis." (PMID 36902241, 2023). "Previous studies have revealed that proposed biomarkers, VCAM-1, ICAM-1, and CD62P with higher concentrations are independently associated with fibrosis." (PMID 31922200, 2020). "Nevertheless, in an adult NAFLD/NASH population, VCAM-1 demonstrates robust performance as a fibrosis biomarker." (PMID 31291245, 2019). "Therefore, VCAM1 could be a common liver-fibrosis-enhancing factor in MASH and hepatitis C." (PMID 39605886, 2024). "However, we must acknowledge the possibility that in end-stage fibrosis or cirrhosis, the VCAM-1 signal could be distorted, as a consequence of reduced accession of the nanobody to the sinusoidal endothelium and transformation (capillarization) of the endothelium." (PMID 36828835, 2023). "VCAM-1 is significantly elevated in serum of NAFLD patients and it has been proposed as clinical biomarker for diagnosis of fibrosis." (PMID 32365632, 2020). "On the other hand, VCAM-1 levels were elevated by 55% (p<0.01) and 40% (p<0.05) in the advanced and mild fibrosis groups compared to no fibrosis cohort, respectively." (PMID 31291245, 2019). "These pilot data support that VCAM-1 molecular imaging could be a first-in-class tool to identify amongst subjects with apparently benign liver disease (i.e., no or mild fibrosis), those with severe liver inflammation—hence the most at-risk for progression." (PMID 36828835, 2023). "In PCV, patients with fibrosis but not those without, had significantly higher levels of ICAM-1 and VCAM-1 compared to controls." (PMID 37985993, 2023). "In contrast to the IL-6 and VCAM-1 results, CRP, TNFα, MCP-1, MIP-1β, and eotaxin levels did not change with fibrosis severity." (PMID 31291245, 2019).
inflammatory bowel disease (12 papers, 2013 to 2025). A spectrum of small and large bowel inflammatory diseases of unknown etiology. "Previous research suggests that, while adhesion molecules like ICAM-1 and MAdCAM-1 also contribute to the treatment of inflammatory bowel diseases, selectively blocking VCAM-1 appears to offer higher potential efficacy in managing these conditions." (PMID 38660311, 2024). "The study found that the expression of P-selectin, ICAM1, and VCAM1 was elevated in the inflamed colon tissue of individuals with inflammatory bowel disease." (PMID 37287987, 2023). "Madcam1 has been linked previously to TNF-α and is an important player in the development of inflammatory bowel diseases, but only few studies describe Madcam1 in the context of retinopathies, in contrast to other adhesion molecules like Vcam1." (PMID 36371417, 2022). "Our imaging study indicates molecular imaging with scFv-VCAM-1 as a promising way for inflammatory bowel disease diagnosis and evaluation." (PMID 30804723, 2019). "Interestingly, a recent study in rats reported that the spore-based probiotic, MegasporebioticTM, lowered serum ICAM-1 levels and, to a lesser extent, lowered serum VCAM-1 levels in the context of inflammatory bowel disease (IBD)." (PMID 36771194, 2023). "For 6 of these genes, a role in inflammatory bowel disease is supported by other criteria: GWAS associations with nearby SNPs (ANKRD55, LPP, PDLIM7), experimental perturbation (CCDC50, VCAM1), association with measured protein levels (IL6, VCAM1), or drug effects (IL6, VCAM1)." (PMID 40996888, 2025). "In a study of kaempferol against inflammatory bowel disease, kaempferol significantly reduced the overproduction of VCAM-1 induced by lipopolysaccharide, indicating the potential role of kaempferol in the regulation of VCAM-1." (PMID 37861497, 2023).
malaria (12 papers, 2011 to 2024). Malaria is a serious and sometimes fatal disease caused by a parasite that commonly infects a certain type of mosquito which feeds on humans. "We also observed the DARC gene, which encodes the Duffy antigen receptor for human malaria, was significantly co-expressed with VCAM1, S1PR1 and ELTD1 in multiple tissues." (PMID 32652930, 2020). "Both ICAM-1 and VCAM-1, soluble adhesion molecules, are detected at high levels in serum from falciparum patients with severe malaria." (PMID 25889165, 2015). "The expression of ICAM-1 and VCAM-1 is consistent with previously reported data indicating these adhesion molecules are expressed during complicated malaria." (PMID 24324686, 2013). "The mechanism of neutropenia in malaria has been postulated to involve increased margination and sequestration of neutrophils as a result of the increased expression of cell adhesion molecules (ICAM-1 and VCAM-1) that occurs in malaria." (PMID 25285308, 2013). "The situation in vivo as to whether levels of soluble VCAM-1 and ICAM-1 are associated with severe malaria is also unclear, but generally the picture is one of a pro-inflammatory disease with concomitant increases in endothelial biomarkers in patients with severe disease." (PMID 22043276, 2011). "In malaria, increased margination and sequestration of neutrophils is explained by the increased expression of cell adhesion molecules (ICAM-1 and VCAM-1)." (PMID 28363279, 2017).
Arthritis (11 papers, 2016 to 2026). Inflammation of a joint. "Aortic vascular mRNA expressions of IL-6 and CXCL-1 were positively correlated while ICAM-1 and VCAM-1 negatively correlated with arthritis score and with radiographic score." (PMID 35488311, 2022). "ICAM-1 and CXCL-1 expression increased in AIA rats at the preclinical phase and at the onset of arthritis while VCAM-1 increased only at the onset of arthritis." (PMID 35488311, 2022). "During arthritis progression, AP-1 controls VCAM-1 production and cell motility." (PMID 39160581, 2024). "By reducing neutrophil recruitment and production of the inflammatory cytokines, BCA attenuated the development of zymosan-induced arthritis in mice, which correlates with the lower expression of adhesion molecules (VCAM-1, ICAM-1, and E-selectin) in neutrophils treated with BCA in vitro." (PMID 33995086, 2021). "As VCAM‐1 specifically reflects large‐vessel inflammation induced by arthritis, this early inflammatory marker may be relevant for evaluating the impact of anti‐arthritic therapies on vascular damage." (PMID 26859834, 2016). "In short, three oleanolic acid glycosides were implied as mainly efficient compounds in Yi nationality herbal formula Wosi for arthritis therapy via selectively influencing COX-2 and VCAM-1 signaling." (PMID 33442381, 2020). "In conclusion, three oleanolic acid glycosides were implied as mainly efficient compounds in Yi nationality herbal formula Wosi for arthritis therapy via selectively influencing COX-2 and VCAM-1 signaling." (PMID 33442381, 2020). "To further validate the mechanism by which MFK902 suppressed arthritis progression, we examined the transcript expression of chemokines (CCL2), adhesion molecules (VCAM-1), MMPs (MMP-1 and -3), and RANKL by semi-quantitative RT-PCR." (PMID 27741237, 2016). "The present study revealed that increased mRNA expression of adhesion molecules (ICAM-1) and CXCL-1 (IL-8) occurred as early as at the preclinical phase of AIA and reached its maximum at the onset of arthritis (ICAM-1, VCAM-1, IL-8) without any changes at the acute inflammatory phase." (PMID 35488311, 2022).
carotid atherosclerosis (11 papers, 2014 to 2025). A thickening and loss of elasticity of the walls of carotid arteries that occur with formation of atherosclerotic plaques. "This suggests an association between carotid atherosclerosis and the local production of not only IL-6 but also E-selectin, VCAM-1 and PTX3." (PMID 24936646, 2014). "This gene is not only a key gene in carotid atherosclerosis, but also its signaling pathway C3a/C3aR1/VCAM1 mediates neuroinflammation in aging and neurodegenerative diseases." (PMID 38694921, 2024). "There was an association between RA patients who harbored carotid atherosclerosis and inflammatory markers such as CRP*, ESR* and IL-6** and VCAM-1*, a marker of endothelial impairment (*p<0.001 and **p<0.05)." (PMID 36249997, 2022). "To determine if VCAM-1 is a good local indicator of carotid atherosclerosis, we evaluated the bifurcation of four 24-month old pigs with the greatest amount of disease." (PMID 26702331, 2015). "Exploiting this platform, we have developed smart molecular magnetic resonance imaging (MRI) probes consisting of dual-targeted microparticles of iron oxide (DT-MPIO) against VCAM-1 and P-selectin, to evaluate the anti-inflammatory effect of statin therapy on progressive carotid atherosclerosis." (PMID 36481841, 2024).
dementia (11 papers, 2018 to 2025). Loss of intellectual abilities interfering with an individual's social and occupational functions. "VCAM1 levels were also significantly associated with the severity of dementia and structure changes of white matter, and brain endothelial VCAM1 at the blood-brain barrier has been proposed as a target for treating age-related neurodegeneration." (PMID 34108016, 2021). "CSF levels of YKL-40, ICAM-1, VCAM-1, IL-15, and Flt-1 were increased during the preclinical, prodromal, and dementia stages of AD." (PMID 30054439, 2018). "Soluble VCAM-1 levels correlate with advanced dementia suggesting that VCAM-1 could be used as a biomarker for cognitive decline in AD patients." (PMID 32911833, 2020). "In the present study, using a large cohort of well-characterized patients, we show increased levels of ICAM-1, VCAM-1, IL-15, and Flt-1in AD at the preclinical, prodromal, and dementia stage, indicating that neuroinflammatory pathways are activated early in the disease course." (PMID 30054439, 2018). "CSF markers of endothelial injury, such as VEGF‐A, ICAM‐1, and VCAM‐1 were associated with elevated Qalb and are also raised in other dementia‐associated diseases, indicating that these changes may not be AD specific." (PMID 41319164, 2025). "Studies have shown that CSF levels of VCAM-1 and ICAM-1 are increased in the preclinical, prodromal, and dementia stages of AD, similar to YKL-40." (PMID 36142483, 2022). "In the dementia group, CSF ApoA1 levels correlated positively with CSF ICAM1 and VACM1 levels [correlation range 0.55 to 0.62, all p < 0.001], while a negative correlation was observed between plasma ApoA1 and CSF ICAM1 and VCAM1, but this correlation was not significant." (PMID 36927447, 2023).
acute myeloid leukemia (10 papers, 2012 to 2025). Acute myeloid leukemia (AML) is a group of neoplasms arising from precursor cells committed to the myeloid cell-line differentiation. "In acute myeloid leukaemia, VCAM1 inhibition or deletion reduced tumour burden and extends survival through restoring clearance by mononuclear phagocytes." (PMID 36494785, 2022). "VCAM1 is highly expressed in acute myeloid leukemia (AML) cells." (PMID 32799626, 2020). "VLA-4 interacts with VCAM-1 to promote Akt, MAPK, NF-κB, and mTOR signaling, while reduce apoptosis in acute myeloid leukemia (AML) cells." (PMID 38736891, 2024). "The interaction between integrin α4β1 and VCAM-1 promotes the activation of AKT, MAPK, NF-κB, and mTOR signals, leading to reduced apoptosis in acute myeloid leukemia cells." (PMID 37932738, 2023). "Thus, at least three adhesion mechanisms, CXCR4/SDF1 (CXCL12), VLA-4/VCAM-1 or fibronectin, and CD44/ligand, function in acute myeloid leukemia migration, retention, and survival." (PMID 22346731, 2012). "When comparing newly diagnosed patients with acute myeloid leukemia (AML) and acute lymphoblastic leukemia (ALL), AML showed a significant increase in IL-4, IL-2 and IL-3, and a significant decrease in VEGF and VCAM-1." (PMID 40427092, 2025).